FCRL3 (Fc receptor like 3)
Diseases named in the same sentence as FCRL3 in open-access papers (continued):
Sharing a sentence is not in itself a finding about the gene and the disease.
asthma (1 paper, 2022). "Many of the upregulated genes in nicotine-treated sperm are known to be involved in asthma pathogenesis, including L-Histidine decarboxylase (Hdc), Fc receptor-like 3 (Fcrl3), Endothelin receptor type B (Ednrb), and Complement C4A (C4a)." (PMID 35600600, 2022).
B-cell lymphoma (1 paper, 2025). "Top proteins that were consistently associated with B-cell lymphoma across the EPIC, ARIC and UK Biobank cohorts included: CXCL13, sCD23, FCRL1, FCRL3, SEMA7A, CD72, CD48, LY9 and VCAM1." (PMID 40894013, 2025). "Strikingly, all the top proteins associated with B-cell lymphoma development (sCD23, FCMR, FCRL1, FCRL3, SELL, SEMA7A and SEMA4A) were most strongly associated with CLL development, suggesting CLL was a major driver of the top protein associations observed in the grouped analysis." (PMID 40894013, 2025).
breast carcinoma (1 paper, 2017). "These include the signaling gene TGFBR1, the proto-oncogene MYB as well as many immune-related genes such as CCR7 and FCRL3, reinforcing evidence for a role of immune components in influencing breast cancer patients’ prognosis." (PMID 28059167, 2017).
celiac disease (1 paper, 2011). An autoimmune genetic disorder with an unknown pattern of inheritance that primarily affects the digestive tract. "Lastly, four of the nine TPOA associated SNPs (in SH2B3, CTLA4, BACH2 and UBASH3A) have also been associated with celiac disease (but not the SNPs in RASGRP1, STAT4, PTPN22, IL2 and FCRL3)." (PMID 21829393, 2011).
cervical cancer (1 paper, 2022). A primary or metastatic malignant neoplasm involving the cervix. "As the expressions of IGSF6, TLR10, FCRL3, and IFI30 were all upregulated in cervical cancer and the higher expressions of IGSF6, FCRL3, and IFI30 predicted better prognosis, we asked if the combination of these four genes was associated with the risks of cervical cancer." (PMID 36387234, 2022). "Consistently, the expressions of IGSF6, TLR10, FCRL3, and IFI30 were upregulated in cervical cancer in the validation cohort." (PMID 36387234, 2022). "To validate the expressions of IGSF6, TLR10, FCRL3, and IFI30 in cervical cancer, we performed immunohistochemistry against these genes, respectively." (PMID 36387234, 2022). "To validate the immune infiltration pattern, the expressions of IGSF6, TLR10, FCRL3, and IFI30, and the correlation between them, we downloaded the GSE151666 dataset from the GEO database as a validation cohort, which included 68 cervical cancer patients." (PMID 36387234, 2022). "By univariant Cox and LASSO analyses, we finally got 4 genes (IGSF6, TLR10, FCRL3, and IFI30) that were closely correlated with both the CD8+ T cell infiltration and the prognosis of cervical cancer." (PMID 36387234, 2022). "In line with the results from the transcriptomics, we identified stronger expressions of IGSF6, TLR10, FCRL3, and IFI30 in cervical cancer tissues compared to normal tissues." (PMID 36387234, 2022). "Apart from this, an intriguing notion is that the four genes (IGSF6, TLR10, FCRL3, and IFI30) were also upregulated in cervical cancer compared to normal tissues, while their high expressions predicted better prognosis." (PMID 36387234, 2022). "Based on these facts, we thought that the discovery of the 4 novel genes (IGSF6, TLR10, FCRL3, and IFI30) in cervical cancer might shed light on the clinical treatments of cervical cancer as well." (PMID 36387234, 2022).
Cirrhosis (1 paper, 2012). A chronic disorder of the liver in which liver tissue becomes scarred and is partially replaced by regenerative nodules and fibrotic tissue resulting in loss of liver function. "ATG16L2, DEFB114, FAM14B, IFNA21, IL8RB and KIR2DL genes were up-regulated in cirrhosis, whereas, FCRL3, IFITM2 and OAS2 genes were up-regulated in initial fibrosis." (PMID 22397681, 2012).
head and neck cancer (1 paper, 2022). A primary or metastatic malignant neoplasm affecting the head and neck. "Genetic polymorphisms of FCRL3 were also associated with the risk of head and neck cancer in a Chinese population." (PMID 35783274, 2022).
Hepatitis C (1 paper, 2020). "Markedly high FCRL2, FCRL3, and FCRL5 were identified in the context of Hepatitis C vaccination." (PMID 32747654, 2020).
lymphoproliferative disorders (1 paper, 2022). "FCRL3 expression is associated with autoimmune and lymphoproliferative disorders, implying a role in promoting B-cell pathogenesis." (PMID 35899045, 2022).
cancer (6 papers, 2012 to 2025). A tumor composed of atypical neoplastic, often pleomorphic cells that invade other tissues. "Among them are cancer-related genes such as MYB and TGFBR1 as well as many immune-related genes such as CCR7 and FCRL3, whose prognostic association is likely to reflect the inflammatory process and the presence of lymphocytic cells in the tumour." (PMID 28059167, 2017). "Compared to uninfected cancers, the infected cancers had significant upregulation of nine cellular factors (FCER2, MS4A1 (CD20), PLUNC, TNFSF9, TRAF1, CXCL11, IFITM1, PPARG, and FCRL3), implying that EBV is not an innocent bystander with respect to biochemical impact." (PMID 22929309, 2012).
tumor (6 papers, 2017 to 2025). "The immunosuppressive functions of FCRL3 (e.g., restricting T cell activation) may create an inflammatory environment in the tumor microenvironment (TME), thereby indirectly promoting NF-κB-mediated inflammatory signaling." (PMID 41367615, 2025). "What is more, there were higher expressions of FCRL3, IFNG, and TRAT1 in recurrent tumor(n = 5) compared with primary tumor(n = 371)." (PMID 34868239, 2021). "Notably, the expression levels of FCRL3 and EFEMP1 are significantly correlated with tumor differentiation, with both genes showing significantly lower expression in G2 (moderately differentiated) tumors compared to G3 (poorly differentiated) tumors." (PMID 41367615, 2025). "Other tumor-specific Treg signature genes (e.g., CCR8, FCRL3, IL1R2) are exclusively expressed on tumor-infiltrating Tregs and absent in their peripheral counterparts." (PMID 33679808, 2021).
infection (4 papers, 2018 to 2024). The state of being infected such as from the introduction of a foreign agent such as serum, vaccine, antigenic substance or organism. "To test the importance of these mutations on FCRL3 clustering and SYK recruitment, we first monitored colocalization of FCRL3, SYK, and Y. pestis in HeLa cells overexpressing FCRL3 at 15-, 30-, and 60-min post infection." (PMID 39677730, 2024). "Secretory IgA (SIgA) is a FCRL3-specific ligand, suggesting pathogen-specific sIgA might drive mucosal regulatory T cell plasticity to help control infection." (PMID 36248887, 2022).
immune disease (2 papers, 2016 to 2025). "The result suggests that these SNPs reported with various auto-immune diseases may be tagging the same functional genetic variants around the FCRL3 gene locus." (PMID 27863461, 2016). "However, increased expression of FCRL3, SKAP2, and AP003774 was associated with lower risk of T1D and RA, while decreased expression of BACH2 and RPS26 increased immune disease risk." (PMID 41361473, 2025).
blood cancers (1 paper, 2024). "Among the proteins associated with risk of haematological cancers, we identified associations with risk of multiple blood cancers for members of the FC-receptor protein [FCRL1, FCRL2, FCRL3, FCRL5, FCRLB] and TNF receptor families [TNFRSF4, TNFRSF9, TNFRSF13B, TNFRSF13C, TNFSF13B, TNFSF13]." (PMID 38750076, 2024).
neurological disease (1 paper, 2025). "Ten proteins showed co-localization with a neurological disease using both plasma protein abundance and plasma mRNA abundance (SIRPA, CTSH and CD33 with AD; and ASF1A, FCRL3, VEGFB, TYMP, PVALB, LMAN2 and CD5 with MS)." (PMID 40037332, 2025).
FCRL3 also shares sentences with these, for which no sentence is quoted: neuromyelitis optica (4 papers); allergic rhinitis (3); hyperthyroidism (2); hypothyroidism (2); rotator cuff tears (2); Addison's disease (1); Alzheimer disease (1); ankylosing spondylitis (1); autoimmune gastritis (1); biliary cirrhosis (1); colorectal adenoma (1); dyslipidemia (1); genetic disease (1); glioblastoma (1); goiter (1); Hashimoto thyroiditis (1); Hypertension (1); Insulin resistance (1); juvenile rheumatoid arthritis (1); lymphoid leukaemia (1); microcephaly (1); myocardial infarction (1); Obesity (1); pancreatic cancer (1); psoriasis vulgaris (1); Se’zary syndrome (1); skin cancer (1); stable angina (1).